CRP (C-reactive protein)
Diseases named in the same sentence as CRP in open-access papers (continued):
Sharing a sentence is not in itself a finding about the gene and the disease.
Insulin resistance (continued). "While we did not study subjects with rheumatic disease, we did look at obese individuals with increased baseline insulin resistance and an elevated baseline CRP, similar to persons with rheumatic disease." (PMID 22676348, 2012). "We found clear elevations in the acute phase reactants CRP and fibrinogen, as well as in insulin resistance among obese adolescents." (PMID 22682228, 2012). "Fibrinogen, CRP, and C3 were positively, whereas albumin was inversely correlated with abdominal adiposity and insulin resistance." (PMID 21822486, 2012). "Similar to insulin resistance, increased levels of fibrinogen, C-reactive protein (CRP) and plasminogen activator inhibitor-1 (PAI-1), liver fat accumulation is an independent risk factor for development of cardiovascular diseases." (PMID 23029000, 2012). "Our main results show a strong and positive correlation between HDL-c and unacylated ghrelin levels in the LHO group, and between HDL-c and adiponectin levels in the MAO group, independently of insulin resistance and hs-CRP levels in both cases." (PMID 22413940, 2012). "The development of insulin resistance can be related to post-traumatic systemic inflammation, even considering the higher leukocytes count and C-reactive protein dosage in insulin resistant patients." (PMID 23031544, 2012). "Emerging laboratory and epidemiological data suggest that CRP is an important plausible factor for insulin resistance, adiposity and other features of the metabolic syndrome." (PMID 21296145, 2011). "These cytokines produced by adipocytes stimulate hepatic synthesis of CRP, which is an acute-phase protein, and influence insulin resistance as well as lipid and glucose metabolisms." (PMID 21663637, 2011). "Inflammatory markers including higher C-reactive protein (CRP) and lower adiponectin concentrations have been associated with insulin resistance." (PMID 21631956, 2011). "Weight, waist and hip circumstances (WHR), body mass index (BMI), metabolic indexes, CRP, ferritin and “Homeostasis Model Assessment of Insulin Resistance (HOMA-IR) ̋ were measured before the study." (PMID 22737516, 2011). "Studies have reported that pro-inflammatory cytokines, tumor necrosis factor (TNF)-α and interleukin (IL)-6, are associated with an increased hepatic C-reactive protein (CRP) synthesis, inflammation, and insulin resistance in humans and animals." (PMID 21554710, 2011). "Metabolic syndrome, C-reactive protein, LDL and HDL cholesterol, and insulin resistance were associated with operated CTS only in subjects aged 45-59 (data not shown)." (PMID 21521493, 2011). "Mean±SD of CRP, ferritin and insulin resistance indexes in three groups of obese, overweight and lean before and after treatment." (PMID 22737516, 2011). "Decreases in TNFα, resistin, interleukin-6, CRP as well as increases in vitamin C or adiponectin were all positive mechanisms to reduce insulin resistance by Cr." (PMID 21167072, 2010). "Correlation between changes of CRP levels with changes of markers of insulin resistance during the study period." (PMID 21179199, 2010). "Levels of HbA1c, fasting insulin, HOMA insulin resistance, triglyceride, and C-reactive protein were higher (though less so than among South Asians) and HDL-cholesterol non-significantly lower." (PMID 20421924, 2010). "Our primary outcomes are serum concentrations of leptin, adiponectin, tumour necrosis factor-alpha, C-reactive protein and interleukin-6 as well as insulin resistance." (PMID 20550712, 2010). "These cytokines produced by adipocytes stimulate the hepatic synthesis of CRP, which is an acute-phase protein, and influence insulin resistance, lipid and glucose metabolism." (PMID 21143879, 2010). "To more precisely define the relationship between insulin resistance and CRP concentration, we further examined this relationship after adjusting for some metabolic factors in addition to age and gender." (PMID 21167068, 2010).
Insulin resistance (continued). "Indian population differs from other population in certain unique biochemical and clinical parameters like increased insulin resistance, higher adiposity, lower adiponectin levels and higher levels of sensitive C-reactive protein." (PMID 20625434, 2010). "In offsprings of diabetic patients Se correlates inversely with CRP and with insulin resistance if Se levels are below 80 μg/l." (PMID 21167072, 2010). "It demonstrates that among hepatic markers only ALT is significantly associated with development of type 2 diabetes independent of classic risk factors as well as markers of whole body insulin resistance (HOMA-IR) and sub-clinical inflammation (CRP)." (PMID 18533046, 2008). "PAI1 was strongly associated with MetS components such as BMI, TG, a homeostasis model assessment of insulin resistance, hs-CRP, and alanine aminotransferase." (PMID 18154661, 2007). "SAD, compared to BMI, WC and WHR, explained a greater portion of the variation in the insulin resistance and CRP levels." (PMID 17391519, 2007). "SAD was the only significant predictor of insulin resistance and level of serum CRP after adjustment for BMI and WC." (PMID 17391519, 2007). "SAD explained a greater proportion of the variation of insulin resistance and CRP levels, even independently of the other anthropometric measures." (PMID 17391519, 2007). "Although CRP levels are related strongly to insulin resistance, it is difficult to conclude if low-grade inflammation induces insulin resistance and the metabolic syndrome or is a consequence." (PMID 17140429, 2006). "Monitoring additional biomarkers to clarify mechanisms, including markers of oxidative stress (e.g., malondialdehyde), inflammation (e.g., high-sensitivity C-reactive protein [hs-CRP]), and insulin resistance (e.g., HOMA-IR), measured at baseline and post-intervention, would also be beneficial." (PMID 41598275, 2026). "Cluster 0 (n = 231) showed metabolically dominant profiles with atherogenic dyslipidemia and insulin resistance, whereas cluster 1 (n = 337) showed inflammation-dominant profiles with preserved lipid levels but elevated high-sensitivity C-reactive protein (hs-CRP)." (PMID 41906614, 2026). "CRP may impair insulin signaling and promote systemic insulin resistance, contributing to glucose dysregulation." (PMID 41200603, 2025). "The use of tools such as the Homeostatic Model Assessment (HOMA) index for evaluating insulin resistance, along with biomarkers such as adiponectin and C-reactive protein, could allow for more precise stratification of metabolic risk in this population." (PMID 40284209, 2025). "In addition, reduced systemic levels of pro-inflammatory cytokines and mediators such as TNF-α and C-reactive protein lead to improvements in insulin resistance and insulin signaling." (PMID 40299548, 2025). "Increased levels of tumor necrosis factor-alpha (TNF-α), interleukin-6 (IL-6), and C-reactive protein (CRP) contribute to insulin resistance, oxidative stress, and enhanced cellular proliferation, creating a microenvironment conducive to CRC development and progression." (PMID 40444236, 2025). "The C-reactive protein–triglyceride–glucose index (CTI), a composite marker of inflammation and insulin resistance, has been linked to various metabolic disorders, but its role in RA remains unclear." (PMID 41255642, 2025). "Consistent with our previous reports, PSO patients had significantly higher Framingham Risk Score (FRS), high sensitivity C-reactive protein (hs-CRP), Body Mass Index (BMI), insulin resistance (HOMA-IR) and total coronary plaque burden, driven by the rupture-prone non-calcified necrotic core." (PMID 39811778, 2025). "Taken together, the association with WHR (abdominal fat), insulin resistance and IL6/CRP might indicate a potential role of BA in inducing and/or maintaining the so-called metabolic inflammation often observed in prediabetes and type 2 diabetes patients." (PMID 40045464, 2025).
Insulin resistance (continued). "For instance, high-calorie diets and confined living conditions promote weight gain and insulin resistance, as reflected by elevated triglyceride-glucose indices (TyG) and C-reactive protein-triglyceride glucose (CTI) scores, which are strongly associated with cardiovascular events." (PMID 41450502, 2025). "However, when the sample was analyzed as a whole, we did observe some relationships between reduced CRP levels and lower body weight, visceral fat mass, and insulin resistance." (PMID 40218888, 2025). "Additionally, CRP levels were found to increase significantly in parallel with higher BMI and insulin resistance." (PMID 40951687, 2025). "These include inflammatory markers (such as C-reactive protein), metabolic syndrome indicators, vitamin D and insulin resistance indicators (such as the insulin resistance index and insulin sensitivity index), which are believed to be potentially associated with the risk of prediabetes." (PMID 39883666, 2025). "In addition, early-onset participants had higher BMI, fasting glucose, HbA1c, insulin resistance index, CRP, total cholesterol, total triglycerides, LDL cholesterol and eGFR." (PMID 40408408, 2025). "Future studies should incorporate imaging data, inflammatory biomarkers (e.g., CRP, IL-6), or metabolic pathways (e.g., insulin resistance, oxidative stress) to investigate potential mechanisms through which WWI may influence PRISm." (PMID 40463466, 2025). "However, when the group was analyzed as a whole, we did observe some relationships between reduced CRP levels and lower body weight, visceral fat mass, and insulin resistance." (PMID 40218888, 2025). "For example, in a study of GDM patients, some inflammatory factors and oxidative stress indicators in serum were found to be associated with insulin resistance, such as increased levels of serum pentraxin-3 (PTX3) and high-sensitivity C-reactive protein (hs-CRP) in GDM patients." (PMID 41488068, 2025). "Most studies reported statistically significant reductions in multiple key inflammatory mediators, particularly TNF-α, IL-6, IL-1β, and CRP, which are central to the pathophysiology of insulin resistance, adipose tissue dysfunction, and cardiovascular complications in metabolic syndrome." (PMID 40868165, 2025). "Even in eutrophic adolescents, but with a high %BF, IL-6 was correlated with other inflammatory cytokines, such as TNF-α and with the development of insulin resistance as well as, with modulating the synthesis of CRP, showing the role of adipose tissue in inflammation." (PMID 40717997, 2025). "It has been well-documented that insulin resistance results in elevated levels of inflammatory factor markers, such as C-reactive protein (CRP) and cytokine interleukin 6 (IL-6), and promotes adverse outcomes of atherothrombosis through an acceleration of the premature atherosclerosis process." (PMID 40313489, 2025). "Compared to those without FL, patients with FL had significantly higher BMI, increased waist circumference, and elevated levels of triglycerides and CRP (P < 0.001), along with greater insulin resistance, as measured by the Homeostasis Model Assessment (P < 0.001)." (PMID 40249657, 2025). "Crucially, chronic inflammation serves as a key mediator in this relationship, with genetic evidence from Mendelian randomization studies confirming that elevated RC directly triggers low-grade inflammation (e.g., increasing C-reactive protein by 28%) and promotes insulin resistance." (PMID 41377565, 2025). "IL-6 may induce insulin resistance and increase the production of CRP in the liver by suppressing the expression of the insulin-sensitive glucose transporter in peripheral tissues." (PMID 40292283, 2025). "Total fat was associated with CMD risk factors, including insulin resistance (OGTT 60 min r = 0.47, p < 0.05; homeostasis model assessment [HOMA] r = 0.62, p < 0.05), serum triglycerides (r = 0.31, p < 0.05), and inflammation (CRP r = 0.43, p < 0.05)." (PMID 40781458, 2025).
Insulin resistance (continued). "This would suggest that participants with the greatest reductions in body weight and visceral fat mass may be more likely to have lower CRP levels, which could help decrease insulin resistance." (PMID 40218888, 2025). "Importantly, GLP-1RAs achieve gradual weight reduction, with studies reporting improvements in insulin resistance, CRP, and homocysteine, as well as clinical gains in Hurley stage and DLQI, without the nutritional deficiencies seen after bariatric surgery." (PMID 41020015, 2025). "To determine whether platelet hyperactivity in the advanced insulin resistance group was agonist-specific, we next tested the effect of CRP-XL." (PMID 40304758, 2025). "Both ferritin and CRP levels reflected systemic inflammation and insulin resistance." (PMID 40507147, 2025). "Specifically, individuals carrying certain CRP single nucleotide polymorphisms (SNPs), particularly rs1205, also known as CRP4, exhibited higher baseline CRP concentrations, independent of traditional risk factors such as BMI or insulin resistance." (PMID 40725102, 2025). "However, with TyG index, age, BMI, triglycerides and CRP were the significant determinants of insulin resistance in participants with past COVID-19 status." (PMID 40273152, 2025). "Elevated levels of chronic inflammatory markers, such as serum interleukin (IL)-6, C-reactive protein (CRP), and tumor necrosis factor-alpha (TNF-α), are associated with lower HGS and physical function and with the development of DM and insulin resistance." (PMID 40283630, 2025). "Reduced blood pressures, fasting serum glucose, insulin levels, insulin resistance, Serum tumor necrosis factor α, C-reactive protein, the total and low-density lipoprotein cholesterol, and triglycerides; increased total antioxidant status and high-density lipoprotein cholesterol." (PMID 39857788, 2025). "Insulin resistance is usually associated with high levels of inflammatory and oxidative biomarkers and mediators namely, tumor necrosis factor (TNF)-α, plasminogen activator inhibitor-1 (PAI-1), C-reactive protein (CRP), interleukin-6 (IL-6)." (PMID 40056319, 2025). "Improved glucose, HbA1c, insulin, insulin resistance, CRP, antioxidant capacity, PON-1." (PMID 40733199, 2025). "In the current study, high CRP levels in obese PCOS patients may explain the increased insulin resistance and HOMA-IR score." (PMID 40572700, 2025). "We observed similar patterns in the validation cohort LLD While being younger as compared to participants in cluster H, LLD participants in cluster U had significantly (p < 0.05) higher BMI, triglycerides, CRP and insulin levels and insulin resistance, while presenting lower HDL_c." (PMID 39834614, 2025). "However, being underweight or overweight compared to normal weight and having high level of CRP compared to the normal level decreased the prevalence of insulin resistance." (PMID 40273152, 2025). "Additionally, these individuals demonstrated elevated insulin resistance, as indicated by the TyG, and higher levels of inflammatory markers, including MS, CRP, SII and SIRI." (PMID 40746546, 2025). "Additionally, prolonged chronic inflammation can lead to insulin resistance, triggered by inflammatory factors such as TNF and C-reactive protein (CRP), resulting in weight loss and decreased albumin levels." (PMID 40443682, 2025). "Additionally, they exhibited significantly higher CRP levels (0.07 mg/dL vs. 0.01–0.04 mg/dL, P < 0.001), and were more likely to be insulin resistance." (PMID 40642596, 2025). "IL-6 and CRP increase during inflammation, impacting glucose metabolism through insulin resistance." (PMID 41404504, 2025). "In addition, CRP has been shown to be an independent risk factor for COPD combined with T2DM and to exacerbate insulin resistance." (PMID 40895616, 2025).
Insulin resistance (continued). "Third, although all analyses were multivariable-adjusted, many important potential confounders were not uniformly included across cohorts, such as inflammatory markers (hs-CRP, IL-6), renal function (eGFR), insulin resistance/HOMA-IR, depression, socioeconomic status, and physical activity levels." (PMID 41375847, 2025). "Recently, some studies have reported a new index related to systemic inflammation (SI) and insulin resistance (IR), the C-reactive protein (CRP)-triglyceride-glucose index (CTI), which can predict the survival of patients with cancer and the poor prognosis of cancer patients with a high CTI." (PMID 39687883, 2024). "In chronic infections such as periodontitis, it has been suggested that elevated serum levels of CRP and other proinflammatories may induce systemic inflammation and oxidative stress, which contribute to the insulin resistance observed in PCOS." (PMID 39768981, 2024). "In the context of the inflammation and metabolic parameters, oncostatin M was inversely correlated with C-reactive protein, homeostasis model assessment of insulin resistance, and low-density lipoprotein cholesterol (ρ = −0.353, p = 0.019; ρ = −0.275, p = 0.048; ρ = −0.470, p < 0.001, respectively)." (PMID 38397957, 2024). "Additionally, in overweight and obese (OB) children, leucine concentrations were significantly elevated, showing a positive correlation with inflammatory markers (CRP, IL-6), SU, visceral adiposity, type 2 diabetes (T2D), insulin resistance, and CVD." (PMID 39027467, 2024). "The change in the oleoylethanolamide/palmitoylethanolamide (OEA/PEA) endocannabinoid ratio following the MedDiet also diminished the homeostatic model assessment of insulin resistance index and decreased serum high-sensitive CRP, a measure of systemic inflammation." (PMID 38978699, 2024). "Insulin resistance was linked to independent cardiovascular risk factors, including MIAP, due to its association with inflammation, such as glycometabolic abnormalities, high-sensitivity C-reactive protein (hs-CRP) levels, and fibrinogen levels." (PMID 38566101, 2024). "Kimchi-derived L. plantarum Ln4 is another strain that reduces weight gain in HFD-fed mice, improves metabolic markers (e.g., reduces total triglycerides and insulin resistance, improves glucose tolerance), and decreases inflammatory adipokines (e.g., CRP, MCP-1) in WAT through immunomodulation." (PMID 39421246, 2024). "However, it is of note that a decrease in CRP concentration in both groups was observed in the subsequent trimesters, despite the increased insulin resistance during pregnancy (Supplement)." (PMID 38308265, 2024). "A limitation of our study is that real-world hospital records lack some parameters, such as waist circumference, high-sensitive CRP and Homeostasis Model Assessment for Insulin Resistance, which are required to evaluate all MAFLD criteria or to calculate some indices of steatosis or fibrosis." (PMID 38829946, 2024). "Laurate-bioconjugated fructans reduced food and energy intake, body weight, body mass index, abdominal circumference, adipose tissue, adipocyte area, serum triglycerides, insulin, insulin resistance, and C-reactive protein but they increased IL-10 protein serum levels and mRNA expression." (PMID 39204141, 2024). "Prolonged chronic inflammation could result in insulin resistance via inflammatory factors like TNF and C-reactive protein (CRP), subsequently causing a decrease in body weight and albumin levels." (PMID 38699426, 2024). "Significant positive correlations were found between atherogenic index of plasma and age, lymphocyte, neutrophil, C-reactive protein, glucose, insulin, and homeostatic model assessment-insulin resistance, while the correlation with platelet/lymphocyte ratio was significantly negative." (PMID 39630767, 2024). "CRP and TNF-α have been associated with insulin resistance and atherosclerosis." (PMID 38566090, 2024).